CXCL12 (C-X-C motif chemokine ligand 12)
Diseases named in the same sentence as CXCL12 in open-access papers (continued):
Sharing a sentence is not in itself a finding about the gene and the disease.
colon carcinoma (continued). "To further evaluate the histone H3 acetylation status in colon cancer, we performed chromatin immunoprecipitation (ChIP) experiments to compare the SW480 colon cancer cell line to HEK293, a human kidney embryo cell line that express CXCL12 at a high level." (PMID 28418886, 2017). "In addition, CXCL12 can regulate the expression of PTEN and affect colon cancer cell proliferation and invasion through PI3K/AKT signaling pathway." (PMID 35770088, 2022). "In this study, we demonstrated that stromal cell-derived CXCL12 induced the suppression of expressed PTEN and enhanced both proliferation and invasion through the activated CXCL12/CXCR4/PI3K/Akt signaling pathway in colon cancer cells." (PMID 31500630, 2019). "Inhibition of microenvironmental CXCL12/CXCR4 signaling may be one approach by which to enhance PTEN phosphorylation, which inhibits colon cancer cell growth." (PMID 31500630, 2019). "The invasion ability of colon cancer cell HT-29 of CXCL12 siRNA group had no significant change compared with the untransfected and control siRNA groups." (PMID 29305742, 2018). "CXCL12 mRNA and proteins were only expressed in DLD-1 colon cancer cell lines." (PMID 29305742, 2018). "While the inhibition of CXCL12 and CXCR4 can significantly reduce tumor cell proliferation and metastasis, indicating that CXCL12 is closely related to development, outcome and prognosis of colon cancers." (PMID 29305742, 2018). "Colon cancer cells forced to endogenously express CXCL12 undergo anoïkis, whereas non-producing cells exogenously exposed to CXCL12 survived and migrated." (PMID 28418886, 2017). "Lentiviral transduction with shRNA to Bim, scrambled transcript, or empty (mock) vectors did not modulate ligand or receptor transcript expression nor CXCL12 secretion in our colonic carcinoma cell lines." (PMID 20877573, 2010). "However, the molecular mechanism of the synergistic regulation of CXCR4/CXCL12 axis and IL-1Ra on colon cancer metastasis is still not clear." (PMID 34930323, 2021). "Growing evidence of colon cancer in vivo indicates that a high expression level of CXCR4 receptor facilitates the non-random extravasation of tumor cells after they have left the primary tumor, especially in the liver, lungs or bone marrow, where CXCL12 is highly expressed." (PMID 28418886, 2017). "Here we also show that forced-expression of PCAF in SW480 non-CXCL12 expressing cells, is a powerful inducer of CXCXL12, providing further evidence that in addition to methylation, level of promoter acetylation may participate to regulate CXCL12 expression in colon cancer cells." (PMID 28418886, 2017). "The activation of the CXCL12/CXCR4 signaling axis leads to chemotaxis, cell survival, and proliferation, however, the downstream signaling cascades are tissue-specific and not well characterized in colon cancer." (PMID 31500630, 2019).
Stroke (71 papers, 2005 to 2026). Sudden impairment of blood flow to a part of the brain due to occlusion or rupture of an artery to the brain. "In this study, we genetically engineered mouse adipose-derived ASCs with CXCL12 variants and transplanted them to the infarct region in a mice transient middle cerebral artery occlusion (tMCAO) model of stroke." (PMID 38255866, 2024). "CXCL12 upregulation is associated with preconditioning process and decreasing neuroinflammation after stroke in ischemic-tolerant mice." (PMID 27635404, 2016). "However, loss of CD13 led to reductions in post-stroke angiogenesis by reducing CXCL12/CXCR4 signaling." (PMID 37817190, 2023). "In addition, other biomarkers such as serum fatty acid binding protein 4 (FABP4), serum CXCL12 levels, interleukin-37, and cystatin C have been reported to be associated with stroke recurrence." (PMID 37051146, 2023). "However, other studies have associated CCL5 and CXCL12 with risk of stroke in human and mouse atherogenesis, promoting cell migration into the brain and induction of cytokines." (PMID 27635404, 2016). "Further research is needed to elucidate the role of CXCL12 in stroke pathophysiology and to determine its potential relevance as a biomarker or therapeutic target." (PMID 42205791, 2026). "We recorded clinical data, plasma CXCL12 levels, and neutrophil phenotype at admission, 24 h and 3 months post-stroke." (PMID 42205791, 2026). "The potential of the monomeric structure of CXCL12 in transducing distinct cellular signals and effects as a potential treatment of stroke remains to be explored." (PMID 38255866, 2024). "Overall, our findings present a novel approach for the engineering of ASC, highlighting the potential of utilizing monomeric CXCL12 to enhance paracrine mechanisms for the treatment of stroke." (PMID 38255866, 2024). "Inhibition of CXCL12 reduced peripheral T cell infiltration and improved neurological deficits post-stroke." (PMID 37817190, 2023). "CXCL12 is a chemokine involved in inflammation and is secreted by multiple cells after stroke including astrocytes, microglia, endothelial cells, pericytes, and neurons." (PMID 37817190, 2023). "The lack of NK cells in Cxcr4Ncr1–/– mice to the lesion in this model suggest that the BBB is essential for the migration of NK cells to the stroke lesion by CXCL12 expression." (PMID 36631780, 2023). "To investigate the role of endothelial cell (EC) CXCL12/CXCR4 pathway after stroke, we then gated on brain ECs as described." (PMID 37817190, 2023). "Flow cytometry was performed on days 3 and 7 post-stroke to quantify infiltrated monocytes and neutrophils and CXCL12/CXCR4 signaling." (PMID 37817190, 2023). "Compared to the controls, we observed a slight decrease only of NK cells in the Cxcl12Cdh5–/– stroke brain at P2 and a significant decrease at P15, indicating that the endothelial-produced CXCL12 is directly involved in the attraction of NK cells." (PMID 36631780, 2023). "Using Cxcl12-DsRed reporter mice, we observed CXCL12 expression in CD31+ endothelial cells within the stroke lesion at P10." (PMID 36631780, 2023). "CD13-deficient mice had an increased percentage of CXCL12+cells but a reduced percentage of CXCR4+cells and decreased angiogenesis at day 30 post-stroke." (PMID 37817190, 2023). "Elevated plasma levels of CXCL12 are a biomarker for predicting acute coronary diseases and potential stroke." (PMID 37298667, 2023). "Elevated plasma levels of CXCL12 are biomarkers for predicting acute coronary disease and future stroke." (PMID 37298667, 2023). "In experimental stroke, a higher percentage of cells were positive for CXCL12 in the CD13KO MCAO animals." (PMID 37817190, 2023). "Based on this profiling data, we first validated the induction of CXCL12 after stroke and observed a substantial increase in protein level expression in peri-infarct cortex compared to uninjured cortex." (PMID 37816732, 2023).
Stroke (continued). "In the subacute phase, stroke patients had an increase in CXCL12-positive area compared to controls, reflecting a stroke-induced increase in CXCL12." (PMID 37817190, 2023). "CXCL12 (=SDF)/CXCR4 binding is a neutrophil retention signal and CXCL12 declines in skull marrow after stroke." (PMID 36246635, 2022). "In human, expression levels of both CXCL12 and ACKR3, but not that of CXCR4, are increased in the peri-infarction area of ischemic cerebral cortex, suggesting that CXCL12 modulates the repair of the brain after a stroke through ACKR3 activation." (PMID 35846294, 2022). "During the postacute phase of stroke, the CXCL12 promotes angiogenesis by recruiting circulating endothelial progenitor cells (EPCs)." (PMID 36052309, 2022). "The stromal cell-derived factor-1 (SDF-1), also called C-X-C motif chemokine ligand 12 (CXCL12) binds to the CXC receptor 4 (CXCR4) as an inflammatory initiator in the acute phase of stroke." (PMID 36052309, 2022). "We explored their therapeutic efficacy and found that intravenously delivered EPCs can home to the ischemic brain and improve long-term stroke outcomes in focal cerebral ischemia, and CXCL12-mediated signaling was involved in EPC-mediated neuroprotection." (PMID 35743941, 2022). "Further investigation into the predominating effect of increased CXCL12 in the post-stroke environment following iPSC treatment is warranted to assess the comprehensive effect on the inflammatory balance." (PMID 33796535, 2021). "What worthy of noting is that, miRNA‐16 is a newly discovered miRNA, which is involved in the progression of stroke by upregulating chemokine CXCL12." (PMID 33880887, 2021). "While SDF-1/CXCL12 is a stroke chemotactic signal for lymphocytes, in the central nervous system it serves to recruit endogenous NSCs to areas of injury for tissue repair." (PMID 33796535, 2021). "Delayed CXCL12 gene therapy promoted neurogenesis and angiogenesis and enhanced functional recovery after stroke." (PMID 34881088, 2021). "One rodent dMCAO model of stroke found a significantly increased expression of SDF-1/CXCL12 (stromal derived factor-1/lymphocyte, C-X-C motif ligand 12) in the peri-infarct area of iPSC-treated animals above that of non-stroked animals." (PMID 33796535, 2021). "In this study, we identified Netrin-1 and CXCL12 as important factors that were involved in the OPC related post-stroke recovery." (PMID 34881088, 2021). "Hampered CXCL12/CXCR4 signaling by AMD3100 downregulates the migration of neuroblasts at the site of ischemic injury 4 weeks after stroke." (PMID 25881123, 2015). "The chemokine stromal-derived factor 1 (SDF-1/CXCL12) is expressed by astrocytes after stroke and mediates attraction of cells by binding to its receptor, CXCR4." (PMID 25191223, 2014). "CXCL12 can play both detrimental and protective roles in stroke." (PMID 37817190, 2023). "Using in situ hybridization, Cxcl12 was observed throughout the brain and increased after stroke." (PMID 36631780, 2023). "However, the percentage of CXCL12+ cells significantly increased in CD13KO compared to wild-type animals on day 7 after stroke." (PMID 37817190, 2023). "CXCL12 was reported to be involved in the migration of CXCR4+ monocytes towards stroke." (PMID 36631780, 2023). "CXCL12 is expressed by multiple cell types including astrocytes, microglia, endothelial cells, and infiltrating immune cells, and its expression is elevated in the brain after stroke." (PMID 37817190, 2023). "This suggests that multiple cell types might be contributing to the stroke-induced increase in CXCL12." (PMID 37817190, 2023). "After brain injury such as stroke or seizures, dead or damaged neurons and reactive glial cells, as well as endothelial cells, may express CXCL12." (PMID 35326336, 2022). "However, there is limited data on the aspect of how the CXCR4/CXCR7/CXCL12 axis modulates neuronal function following stroke." (PMID 35401118, 2022).
Stroke (continued). "CXCL12, which was one of three genes in the pathway, and its receptor CXCR4, which is also the coreceptor of HIV, participate in the pathogenesis of CNS disorders such as HIV-associated encephalopathy, brain tumor, stroke, and multiple sclerosis." (PMID 35456082, 2022). "Increased levels of CCL5, CCL2, CCL3, and CXCL12 found in the early phase of endothelin-1 induced stroke model were not the cause of neurodegeneration." (PMID 27635404, 2016). "CXCL12 is reported to play a critical role in neuroprotection after stroke, by recruitment of endothelial progenitor cells and neuronal progenitor cells in the subventricular zone (SVZ) as well as by promoting proliferation, differentiation, and migration of those progenitor cells." (PMID 27635404, 2016). "Several studies have indicated a protective role for CXCL12 in stroke-induced brain injury." (PMID 24920309, 2014). "Indeed, increased plasma levels of CXCL12 reportedly could predict acute coronary diseases and future stroke." (PMID 33119719, 2020). "Mechanistically, miR-181a-5p inhibition regulates cell survival in neurons and astrocytes after forebrain ischemia and stroke, and lncRNA SNHG1 promotes neuronal injury in a Parkinson’s disease cell model via the miR-181a-5p/CXCL12 axis." (PMID 36998510, 2023). "The expression of the chemokine CXCL12 and its receptor CXCR4 within the brain increases after stroke, which plays a critical role in the migration of monocytes to brain parenchyma." (PMID 36631780, 2023). "Our data show a role for blood–brain barrier-derived CXCL12 in attracting protective NK cells to ischemic brain lesions and identifies a new CXCL12/CXCR4-mediated component of the innate immune response to stroke." (PMID 36631780, 2023). "Our group found that AAV-mediated CXCL12 expression upregulated the proliferation of NSCs in SVZ and migration of neuroblasts to the peri-infarct region, thus promoting neurogenesis post-stroke." (PMID 35743941, 2022). "Following stroke, an accumulation of CXCR4 positive cells, including neurons, is observed in the peri-infarct area accompanied with increased levels of CXCL12, the endogenous ligand of the CXCR4." (PMID 34417725, 2021). "CXCL12 levels are increased in most pathological conditions that CXCR7 is overexpressed in, including tumors, rheumatoid arthritis, stroke, multiple sclerosis, traumatic brain injury and obesity." (PMID 32098047, 2020). "In the stroke model, stem cells are chemo-attracted to the site of the infarction by cytokines with one molecular pathway being CXCR4/CXCL-12 (SDF-1) signaling." (PMID 27013982, 2016). "Interestingly, common pathways are activated after stroke during different recovery periods, with some, like the metalloproteinase (MMP) family and chemokine stromal-derived factor-1 (SDF-1 or CXCL12), displaying a biphasic nature." (PMID 39451997, 2024). "However, our studies validating the involvement of CD13 and CXCL12/CXCR4 in human stroke patients, that were older and both sexes (mean age − 61–92 years) suggests that this is also relevant to clinical stroke." (PMID 37817190, 2023). "Blocking post-RHP CXCL12 expression with a CXCL12 receptor (CXCR4) antagonist AMD-3100 disrupted beneficial CXCL12/CCR4 signaling after RHP, and attenuated the anti-inflammatory effect of RHP in the post-stroke brain." (PMID 27492770, 2016). "A significant interaction effect of age and stroke was seen in CXCL12 levels (Two-way ANOVA, p<0.0001), with aged animals showing higher levels of CXCL12 (p=0.05) under sham conditions, but significantly lower levels of CXCL12 (p=0.006) than young animals after ischemic stroke." (PMID 31927534, 2020). "CXCL12 and CXCR4 are constitutively expressed and widely detected in the CNS, especially in microglia, and have been shown to play important roles in the physiology of the brain and in pathological conditions, such as stroke, multiple sclerosis (MS), and some neurodegenerative diseases." (PMID 31831012, 2019).
pulmonary fibrosis (68 papers, 2008 to 2026). Chronic progressive interstitial lung disorder characterized by the replacement of the lung tissue by connective tissue, leading to progressive dyspnea, respiratory failure, or right heart failure. "These events cause the production of CXCL12 and the eventual recruitment of profibrotic segregated-nucleus-containing atypical monocytes (SatMs) to initiate pulmonary fibrosis distinct from the conventional growth factors-driven fibrosis pathway." (PMID 36164329, 2022). "Our results present a signaling pathway associated with CXCL12 and the profibrotic protein, CTGF, and provide support for the development of therapeutic strategies to reduce pulmonary fibrosis caused by CXCL12." (PMID 25121739, 2014). "In an animal study described in the literature, where single-cell RNA sequencing was performed after bleomycin administration, an increase in endothelial cells characterized by Cxcl12 was observed in bleomycin-induced pulmonary fibrosis." (PMID 41302962, 2025). "Loss of Twist1 in mesenchymal collagen-producing cells increases bleomycin-induced pulmonary fibrosis by up-regulating Cxcl12 expression in mice, highlighting the crucial role of the CXCR4-CXCL12 axis in IPF pathogenesis." (PMID 39768150, 2024). "Neutralization of Cxcl12 or blocking the Cxcr4 receptor reduces bleomycin-induced lung fibrosis by diminishing the pulmonary influx of circulating fibrocytes." (PMID 39768150, 2024). "For example, CXCL12 can mediate the recruitment of fibrocytes, which exacerbates bleomycin-induced pulmonary fibrosis." (PMID 38716725, 2024). "Chemokines, such as CXCL12, CCL1, and CCL18, are implicated in pulmonary fibrosis, acting as chemoattractants by combining with the chemokine receptors, and yet the role of CXCL16 and its receptor remain poorly understood." (PMID 38789926, 2024). "iDESC also identified CXCL12, a gene potentially related to the pulmonary fibrosis progression, to be upregulated in IPF fibroblast." (PMID 37608264, 2023). "CXCR4/CXCL12 axis which is involved in the control of lung fibroblast activity has been shown to be required for fibrocyte participation in the pathogenesis of lung fibrosis." (PMID 36164329, 2022). "Our identification within IPF tissue of high expression of CXCR4 in the immune infiltrate ROIs and the expression of CXCL12 within fibroblastic foci suggests a potentially similar immune exclusion mechanism in lung fibrosis." (PMID 35977489, 2022). "While AMD3100 has been tested in preclinical models of lung fibrosis, its prophylactic antifibrotic activity was attributed to prevention of CXCL12-mediated migration of circulating fibrocytes into the injured lung." (PMID 35977489, 2022). "Prior studies have shown increased infiltrating mast cell numbers and tryptase activity in human IPF, and therapeutic targeting of CXCL12/CXCR4 signaling attenuated bleomycin induced lung fibrosis in mice." (PMID 34689792, 2021). "The mobilization of circulatory fibrocytes and BM-derived primordial germ cells into injured lungs is controlled by the CXCL12/CXCR4 axis promoting the pathogenesis of pulmonary fibrosis." (PMID 34082837, 2021). "CXCR4 is the main chemokine receptor expressed on circulating fibroblasts in humans and mice, and there is a direct correlation between the lung and plasma levels of CXCL12 and the number of circulating pulmonary fibrocytes in patients with pulmonary fibrosis." (PMID 34001199, 2021). "CXCL12, an essential chemokine for wound healing and tissue homeostasis, is also important for lung fibrosis development by regulating the migration of pro-fibrotic monocytes such as fibrocytes and SatMs." (PMID 32708315, 2020). "Previous studies examined the role of the CXCL12/CXCR4 system in lung fibrosis and demonstrated an essential role in fibrosis development, although the detailed mechanisms remain to be clarified." (PMID 32708315, 2020).